MON2 (MON2 regulator of endosome-to-Golgi trafficking)
Description:
Plays a role in regulating membrane trafficking of cargo proteins. Together with ATP9A and DOP1B, regulates SNX3 retromer-mediated endosomal sorting of WLS away from lysosomal degradation.
Synonyms: KIAA1040
Tractability: PROTAC: ubiquitination databases record sites on it; its protein half-life has been measured.
Gene: Protein-coding gene on chromosome 12 (62,466,799 to 62,600,476, forward strand). Ensembl gene ENSG00000061987.
Subcellular location: Early endosome membrane
Subcellular location (Human Protein Atlas): Nucleoli fibrillar center; Nucleoplasm
Gene Ontology:
Molecular function: identical protein binding; protein binding
Biological process: Golgi to endosome transport; protein targeting to vacuole; regulation of retrograde transport, endosome to Golgi; retrograde transport, endosome to Golgi
Cellular component: early endosome membrane; extracellular exosome; Golgi apparatus; endolysosome; endoplasmic reticulum; cytosol
Genetic constraint (gnomAD): Loss-of-function variants: 51 observed, 151.31 expected, observed/expected ratio (o/e) 0.34, 90% interval 0.27 to 0.43. The upper end of that interval is the gene's LOEUF score, 0.43, which puts it in group 1 of 6, group 1 being the genes least tolerant of losing a copy. Missense variants: 1,324 observed, 1,755.3 expected, observed/expected ratio (o/e) 0.75, 90% interval 0.72 to 0.79. Synonymous variants: 562 observed, 623.37 expected, observed/expected ratio (o/e) 0.9, 90% interval 0.84 to 0.97.
Homologues: Orthologues: chimpanzee MON2 (99% identical), macaque MON2 (99% identical), pig MON2 (98% identical), rabbit MON2 (98% identical), dog MON2 (97% identical), rat Mon2 (95% identical), mouse Mon2 (95% identical), guinea pig MON2 (94% identical), tropical clawed frog mon2 (89% identical), zebrafish mon2 (83% identical), Drosophila melanogaster mon2 (48% identical), Caenorhabditis elegans mon-2 (32% identical). Paralogues in human: ARFGEF2 (11% identical), ARFGEF1 (11% identical), GBF1 (11% identical), IQSEC1 (11% identical), IQSEC2 (10% identical), IQSEC3 (10% identical), PSD3 (9% identical), PSD2 (9% identical), PSD (9% identical), PSD4 (8% identical), CYTH2 (6% identical), CYTH3 (6% identical), and 3 more.
Diseases named in the same sentence as MON2 in open-access papers:
MON2 is named in the same sentence as 15 diseases in open-access papers, as found by Europe PMC text mining. Sharing a sentence is not in itself a finding about the gene and the disease. The quoted sentences say what the papers report.
myocardial infarction (3 papers, 2017 to 2023). Gross necrosis of the myocardium, as a result of interruption of the blood supply to the area, as in coronary thrombosis. "In this regard, our results revealed that Mon1 and Mon2 were highly related to the serological markers of plaque rupture and myocardial infarction." (PMID 29047360, 2017). "At the same time, Mon2 are enriched in the region of the myocardial infarct damage." (PMID 36593308, 2023).
atherosclerosis (2 papers, 2017 to 2019). A disease characterized by the build-up of fatty material and calcium deposition in the arterial wall resulting in partial or complete occlusion of the arterial lumen. "In this context, increased numbers of Mon2 and Mon3 subtypes in hyperlipidemia has been associated with atherosclerosis development, and other studies have noted an enhancement in circulating CD16+ monocytes (Mon2 and Mon3) in CVD, which is possibly linked to disease outcome." (PMID 31109070, 2019).
atrial fibrillation (1 paper, 2020). A disorder characterized by an electrocardiographic finding of a supraventricular arrhythmia characterized by the replacement of consistent P waves by rapid oscillations or fibrillatory waves that vary in size, shape and timing and are accompanied by an irregular ventricular response. "Interestingly, in several specific patient populations with atrial fibrillation, heart failure and chronic kidney disease, Mon2 were an independent predictor for cardiovascular events." (PMID 31969629, 2020).
breast carcinoma (1 paper, 2023). "One study has shown that MON2 is overexpressed in breast cancer cells and is associated with a poor prognosis in breast cancer patients." (PMID 37538932, 2023). "The study suggests that MON2 may promote the proliferation and invasion of breast cancer cells by regulating endosome-to-Golgi trafficking." (PMID 37538932, 2023).
clear cell renal carcinoma (1 paper, 2023). A malignant epithelial neoplasm of the kidney characterized by the presence of lipid-containing clear cells within a vascular network. "Furthermore, protein MON2 homolog (MON2) regulated by microRNA-133a-5p inhibits metastatic capacity of clear-cell renal carcinoma." (PMID 36979661, 2023).
delirium (1 paper, 2020). A disorder characterized by confusion; inattentiveness; disorientation; illusions; hallucinations; agitation; and in some instances autonomic nervous system overactivity. "Mon2 produce IL6 under stimulation, which may possibly explain the association of elevated Mon2 with extracardiac complications such as delirium and AKI after cardiac surgery." (PMID 31969629, 2020).
metabolic syndrome (1 paper, 2019). A cluster of metabolic risk factors for CARDIOVASCULAR DISEASES and TYPE 2 DIABETES MELLITUS. "Along this line, an analysis of our results suggests that the increase of the Mon2 and Mon3 populations that are found in metabolic syndrome is likely due to a phenotypic shift of Mon1 monocytes." (PMID 31109070, 2019).
preeclampsia (1 paper, 2022). Preeclampsia is a hypertensive disorder of pregnancy that is characterized by new-onset hypertension with proteinuria presenting after 20 weeks of gestation, and depending on mild or severe forms may initially present with severe headache, visual disturbances, and hyperreflexia. "Previous work has shown Mon2 to be increased, and make up a greater proportion of the monocyte count in women with preeclampsia, with counts correlating with disease severity." (PMID 35725746, 2022).
cancer (3 papers, 2016 to 2023). A tumor composed of atypical neoplastic, often pleomorphic cells that invade other tissues. "Furthermore, the crucial role of microsatellite instability (MSI) status in the field of cancer immunotherapy prompted us to examine the association between MON2 expression and MSI status." (PMID 34980132, 2022). "There is limited research on the role of MON2 in cancer, but some studies have suggested that MON2 may play a role in the development and progression of certain types of cancer." (PMID 37538932, 2023). "Given that MON2 expression could be a potential factor affecting immunotherapy response, we delineated the distribution of MON2 expression across different cancer types and immune subtypes." (PMID 34980132, 2022). "In particular, the overexpression of lnc-PTPDC1-7, lnc-USP25-2, and lnc-MON2-2 that overlap host genes for members of the let-7 family may somehow be related to this miRNA downregulation often detected in cancer." (PMID 26895470, 2016).
tumor (2 papers, 2013 to 2022). "Our results suggested that the loss-of-function of MON2 was associated with an enhanced response rate to ICBs, uncovering a new role of this gene associated with tumor immunity." (PMID 34980132, 2022). "These analyses collectively showed that the loss of MON2 was closely related to enhanced tumor immunogenicity." (PMID 34980132, 2022). "Collectively, inhibition of MON2 might lead to the augmentation of anti-tumor immunity, which might open new possibilities for treating tumors with high MON2 activity." (PMID 34980132, 2022). "Based on our findings, MON2 inhibition could be a potential therapeutic strategy with the ability to augment immune-induced tumor killing." (PMID 34980132, 2022). "Since MHC scores were used to measure the antigen presentation ability of tumor cells, we hypothesized that MON2 might be more relevant to tumor cell-intrinsic immune-associated factors." (PMID 34980132, 2022). "The product can be observed in sample SN214 (TCGA-74-6583) but not in non-tumor brain and MON2-MARS fusion negative GBM samples." (PMID 24261984, 2013).
MON2 also shares sentences with these, for which no sentence is quoted: chronic kidney disease (1 paper); heart failure (1); hyperlipidemia (1); neurodevelopmental disorder (1); psoriasis (1).